TNF (tumor necrosis factor)
Diseases named in the same sentence as TNF in open-access papers (continued):
Sharing a sentence is not in itself a finding about the gene and the disease.
colon carcinoma (continued). "Similar findings have been shown in cervical carcinoma (HeLa), where IMP significantly inhibited the tumor necrosis factor (TNF)-α-induced expression of cyclin D1 and in HT-29 colon cancer cells affected by IMP treatment, resulting in cell cycle arrest in the G1 phase and apoptosis induction." (PMID 32353989, 2020). "In conclusion, we report that miR-21 is not linked to expression of the pro-inflammatory cytokine TNF-α mRNA, but that miR-21 and TNF-α both take part in the cancer expansion at the invasive front of colon cancers." (PMID 30999696, 2019). "The treatment of colon cancer cells with TNF-α resulted in an increase in LAMA5 expression; an effect not demonstrated in endothelia." (PMID 31064120, 2019). "The role of tRXRα expression in myeloid cells was also illustrated by increased macrophage infiltration and mRNA expression of IL-6, IL-11, and TNFα in colon tumor tissues from LysM-tRXRα but not in LysM-RXRα mice." (PMID 30931933, 2019). "Therefore, we examined the effect of MA-35 on the TNF-α signal transduction pathway and TGF-β1 pathway using the human colon cancer cell line HT-29." (PMID 31484999, 2019). "The linkage of zerumbone inhibiting TNF-alpha and its role in the proliferation of colon cancer cell has never been reported or study." (PMID 29511228, 2018). "Given that only activated-hMSCs promote colon cancer progression but not inactivated hMSCs, we focused on TNF-α preactivated-hMSCs in the following mechanistic study." (PMID 28542126, 2017). "Some inflammatory factors, such as IL-1β and TNF-α, may stimulate a sustained COX-2 expression and PGE2 production in colonic tissues, promoting proliferation and invasiveness of colon cancer epithelial cells." (PMID 28676858, 2017). "Strikingly, pharmacological inhibition of paracrine/autocrine TNFα signaling by the TNFα scavenger Enbrel rescues HT-29 colon carcinoma cells, but not A172 glioblastoma cells from IFNα/BV6-induced cell death." (PMID 26788912, 2016). "26, TNF-α induced PUMA expression in HCT116 cells, a human colonic cancer cell line." (PMID 27271344, 2016). "Tumor necrosis factor-α (TNF-α), a pro-inflammatory cytokine involved in the initiation and propagation of CRC, upregulates 5-LOX, LTC4 synthase and CysLT1 while downregulating CysLT2 expression in SW-480, HCT-116, HT-29, and Caco-2 colon cancer cells." (PMID 27709113, 2016). "Using the human colon carcinoma T84 cell line and the murine myeloid J774 cell line as in vitro model systems, we observed that both IFNγ-activated Jak-STAT and LPS/TNFα-activated NF-κB are essential for iNOS induction in both the tumor cells and the myeloid cells." (PMID 26497740, 2015). "The inhibitory effect of TNFα on CYP27B1 and TRPV6 expression in colon cancer cells might alter calcium uptake in the inflamed intestine." (PMID 24120915, 2014). "Moreover, Interferon-α upregulates MDR1 mRNA and P-gp expression in ovarian cancer, and in colon cancer, and MRP mRNA is upregulated by TNF-α." (PMID 23857432, 2013). "NPA scoring was then applied to different inflammatory and cell cycle-related HYPs using two transcriptomic data sets: a TNFα dose and time series in normal human bronchial epithelial (NHBE) cells and a CDK inhibitor R547 dose and time series in HCT116 colon cancer cells." (PMID 22651900, 2012). "To determine whether these two conflicting pathways co-exist and interferes with each other, we examined TNFα-induced NF-κB activation and the effects of blocking NF-κB activation on TRAIL-induced apoptosis in human colon carcinoma cell line SW480." (PMID 21264227, 2011). "Furthermore, we demonstrated that TRAIL therapy and TNFα/IFN-γ-producing T cell immunotherapy, when used in combination, can effectively suppress colon carcinoma metastasis in vivo." (PMID 21264227, 2011).
colon carcinoma (continued). "Thus, our data revealed a synergistic cooperation between TNFα and IFN-γ in sensitizing metastatic colon carcinoma cells to TRAIL-mediated apoptosis in vitro and in suppressing colon carcinoma metastasis in vivo." (PMID 21264227, 2011). "However, the specific effects of collagen peptides on TNF-α expression in colon carcinoma cells are not well-documented." (PMID 40699763, 2025). "In addition, O. splanchnicus showed a significant positive correlation with MUC2, ZO-1, Claudin, and IL-10, and a significant negative correlation with colonic tumor numbers, tumor volumes, advanced colonic lesions, TNF-α, and IL-1β." (PMID 39924893, 2025). "NFkB signaling was found to foster colorectal cancer cell proliferation, whereas TNF-α instigated the PI3K/Akt signal transduction pathways, subsequently stimulating the downstream NF-κB pathway p65, culminating in the augmentation of metastatic capabilities in colon cancer cells." (PMID 39075485, 2024). "In this regard, recent research has shown that colon cancer cells release a spectrum of factors into the TME, including TNF-α, interleukin-6 (IL-6), interleukin-8 (IL-8), plasminogen activator inhibitor-1 (PAI-1), MMP1, and tumor-derived miRNAs that may contribute to this process." (PMID 37760840, 2023). "Herein, using a murine model of intestinal-type colon cancer we report the presence of high levels of SCF and IL-33 in the TME which coincides with the accumulation of TAMCs with a connective-like phenotype that through the production of TNF-α and IL-6 contributes to a pro-inflammatory environment." (PMID 37730723, 2023). "Therefore, anti TNF-α Ab did not inhibit colon cancer cell lines in vitro, but inhibited colon cancer development in mice in vivo." (PMID 37185713, 2023). "Interestingly, by using Tspan8-deficient HT29 colon carcinoma cells, we observed that while Tspan8 promoted cleavage of the ADAM17 substrate TNF α, it did not alter ADAM17-mediated shedding of TNFR1." (PMID 36078095, 2022). "In addition, it was long-time established that TNF-α and INF-γ have a strong effect in inhibiting colon cancer cell proliferation, and a combination of these cytokines could resulted in 30–40% more growth inhibition in CRC cell lines." (PMID 35296257, 2022). "In addition, in HCT-116 human colon cancer cells stimulated by tumor necrosis factor (TNF)-α, TUDCA significantly reduced the expression of IL-8 and IL-1α, and inhibited TNF-α-induced phosphorylation/degradation of IκBα, along with the inhibition of NF-κB DNA-binding activity." (PMID 35806184, 2022). "However, it has been shown that the colon cancer cell line HTM-29 cannot secrete IL-6 upon IL-1β- or TNF-α-stimulation, because these cytokines do not lead to NF-κB activation here." (PMID 34671021, 2021). "Whilst this was consistent with the notion that inflammation modulators contribute to DNA damage, our original hypothesis that TNF-α modulates BaP and PhIP induced DNA damage in colon cancer epithelial cells was not supported." (PMID 33961948, 2021). "Antiproliferative and pro-apoptotic synergy of IFN-γ and TNF-α have been reported in various non-Treg cell types, including colon carcinoma, neuroblastoma, salivary ductal cell lines, and pancreatic beta cells, and the specific signaling cascades are partially defined." (PMID 32005826, 2020). "In either human colon cancer HT29 cells with endogenously RIP3 expression or HeLa-RIP3 cells with exogenously expressed Flag-tagged RIP3, necroptosis could be induced by TNF plus a pan-caspase inhibitor Z-VAD-FMK (Z-VAD) and Smac-mimic small molecule compound (Smac-mimic)." (PMID 33195272, 2020). "A study on colon cancer-derived cells, HCT116, Caco-2, and SW480, treated with 20 nM 1,25-OHD for 24 h and followed by 100 ng/mL TNF-α for 12 h, revealed that vitamin D may maintain the intestinal epithelial barrier permeability by suppressing NF-κB activation." (PMID 32422882, 2020).
colon carcinoma (continued). "Whilst we could phenocopy the effect of myeloid cell-conditioned media with recombinant TNFα alone, with respect to LAMA5 in colon cancer cells, it remains to be determined whether other factors produced by tumour-derived myeloid cells can similarly drive LAMA5 expression." (PMID 31064120, 2019). "Moreover, significant correlation between the TNF-α mRNA expression level in CRC tumor tissue, and prevalence of TNF-α -857 CT and TT genotypes were reported and may be involved in the progression of colon cancer." (PMID 26572151, 2016). "It was demonstrated that pretreatment of a colon cancer cell line with commercial PG juice (6–50 μg/mL), total pomegranate tannins (TPT, 30–200 μg/mL), and punicalagin (25–200 μg/mL) inhibited AKT activity, NF-κB activation, and COX-2 expression induced by TNFα." (PMID 23573120, 2013). "Furthermore, sialylated Lewis a and Lewis y were related with apoptosis; in this sense, Rapoport and Le Pendu found in colon carcinoma cell lines such as HT29 in which apoptosis was induced by UV irradiation, TNFα and anti-Fas, a major decrease of this antigen as well as Lewis x." (PMID 19715603, 2009). "In vitro effects of docetaxel on the human colon carcinoma cell line HT-29 have been studied with respect to the expression of different adhesion and surface marker molecules, the adhesion and immunocytotoxicity of peripheral blood lymphocytes and the secretion of IFN-γ and TNF-α." (PMID 12085250, 2002). "Likewise, TNF production from γδ T cells may not be crucial for the overall cytokine balance in colon tumours, while γδ T cells produce IFN-γ to an extent comparable to or higher than conventional αβ T cells." (PMID 38953978, 2024). "However, in U937 human leukemic cells, MEF cells, macrophages and rat colon carcinoma REG cells, HSPB1 appears to enhance NF-κB activation in response to either etoposide or TNF-α treatment, suggesting that the outcome of NF-κB regulation by HSPB1 may vary with cell type or stimuli." (PMID 29662435, 2018). "We therefore hypothesize that the usual hypovascularity of colorectal metastases in patients explains the lack of TNF-benefit in the experience as described by Alexander in patients, which correlates closely to our observations in our hypovascular colon cancer liver metastases model in rats." (PMID 12610519, 2003). "Although colon cancer cells that were co-transfected with TOP-flash and FOP-flash reporter plasmids were either stimulated with TNF or overexpressed with the p65 plasmid, we did not detect any significant changes in terms of β-catenin activity." (PMID 37185280, 2023). "Collectively, these findings suggest that TNF-α induced DNA damage involves JNK signaling pathway rather than AhR and NF-κB pathways in colon cancer epithelial cells." (PMID 33961948, 2021). "Results showed that although the antitumor effect on breast and colon cancer models of anti-CD40 decreased, the most suitable combination was simultaneous rather than delayed treatment with anti-TNFα administration." (PMID 33540543, 2021). "Nevertheless, polyI:C did not induce TNFα, IL-1β, IL10 and IL-12p40 in HCC and colon cancer cell lines tested." (PMID 28427199, 2017). "A Polish study between 2004 and 2006 already demonstrated the role of TNF-α and its receptors TNFR2 and TNFR2/R7 (without exon 7) and the expression in colon cancer tissues, depending on clinical stage of disease." (PMID 27110571, 2016). "As in the early phase of DSS induction, colonic tumor IL-6 (P<0.05) and possibly IL-11 (P = 0.07) mRNA expression was higher in Iron/DSS compared with Control/DSS mice but not TNF or IFNγ." (PMID 24223168, 2013). "Nonetheless, our results are consistent with recent observations in HCT116 colon cancer cells, where HDACI treatment or depletion of HDAC2, but not HDAC1, sensitizes towards TNFα-induced apoptosis." (PMID 20398369, 2010).
colon carcinoma (continued). "Gastrin‐SiO2 microspheres (20 mg kg−1 day−1, 80 μL/10 g), administered by gavage (10–20 s), did not affect the mRNA expression of inflammatory factors (TNFα, MCP‐1, MCP‐2, IL‐1β, and IL‐6) in the intestine and colon cancer promoting markers in the serum (CEA, CA199, and PSA)." (PMID 39950948, 2025). "Similarly, in HCT-116 colon cancer cells, VDR expression was significantly increased, whereas TNFα expression showed no statistically significant change." (PMID 41444742, 2025). "Interestingly, the intratumorally administration of a combination of TNF-α and IFN-γ suppresses the tumour growth in a human colon cancer model, while independent treatment does not induce these effects." (PMID 38077402, 2023). "Therefore, TNFα and IFN-γ-mediated sensitization of colon carcinoma cells to TRAIL-induced apoptosis does not depend on increasing DR4 and DR5 expression or decreasing T-R3 and T-R4 expression." (PMID 21264227, 2011).
Alzheimer disease (520 papers, 2005 to 2026). A progressive, neurodegenerative disease characterized by loss of function and death of nerve cells in several areas of the brain leading to loss of cognitive function such as memory and language. "KEGG pathway analysis identified several relevant pathways, including Alzheimer’s disease, neurodegeneration-associated pathways, apoptosis, the TNF signaling pathway, and cancer-related pathways." (PMID 40650064, 2025). "On the other hand, TNF-α is a critical player in neuroinflammatory processes associated with neurodegenerative diseases including Alzheimer’s disease, Parkinson’s disease, and multiple sclerosis." (PMID 40430212, 2025). "Multiple lines of evidence implicate TNF-α and its receptors as potential risk factors for Alzheimer’s disease (AD)." (PMID 40297494, 2025). "A higher BMI and lower TNF-α also associated with a higher volume of the Alzheimer’s disease signature region." (PMID 39883521, 2025). "Elevated levels of IL-1β, IL-6, MCP-1, and TNF-α, alongside reduced IL-8 and IL-10 levels, suggest a robust inflammatory response associated with Alzheimer’s disease." (PMID 40711681, 2025). "TNF-α has potential to damage human brain cells and disrupt the physiology of neuronal cells and is implicated in neuronal necroptosis in Alzheimers disease." (PMID 40597958, 2025). "Previous studies have shown that sleep deprivation raises neuroinflammatory biomarkers such as TNF, IL-6, and β-amyloid protein, which is linked to Alzheimer's disease." (PMID 40390711, 2025). "Systemic inflammation induced by the activation of Toll-like receptors (TLRs) and inflammatory mediators such as TNFα has been suggested to cause cognitive decline and accelerate the progression of Alzheimer’s disease." (PMID 38822888, 2024). "In fact, elevated levels of TNFα have been linked to CNS disorders such as Alzheimer’s disease, Parkinson's disease, and multiple sclerosis." (PMID 39361032, 2024). "Due to the strong association with cognitive decline (like Alzheimer’s disease), it’s difficult to announce TNF-a as a potential biomarker of delirium which demands further research to clarify the specific role of TNF-a in delirium development." (PMID 39700095, 2024). "For instance, the increase in TNF-α associated with acute and chronic systemic inflammation is linked to the enhanced cognitive decline in Alzheimer’s disease." (PMID 39114530, 2024). "Elevations in proinflammatory cytokine levels (e.g., IL-1β, IL-6, and TNFα) are implicated in the development of Alzheimer's Disease [AD]." (PMID 39055623, 2024). "Possession of the TNF-alpha T allele significantly increases the risk of vascular dementia and increases the risk of Alzheimer’s disease associated with apolipoprotein E (APOE)." (PMID 37570816, 2023). "TNF-α, a common pro-inflammatory biomarker, has been considered to be associated with a cognitive decline in patients with Alzheimer's disease." (PMID 37649721, 2023). "Such a mechanism involving elevated systemic levels of TNF was proposed to cause accelerated cognitive decline in patients with Alzheimer’s disease." (PMID 37143648, 2023). "Resveratrol is proven to suppress the expression of pro-inflammatory molecules such as NF-kB and TNF-α in glial cells, while also increasing the amount of the anti-inflammatory cytokine IL-10, which is linked to Alzheimer’s diseases." (PMID 35651632, 2022). "Etanercept has been shown to be effective in patients with Alzheimer’s disease, in which it was suggested that it reversed neuronal excitability associated with TNF-α exposure by acting as a decoy receptor." (PMID 35207270, 2022). "Tumor necrosis factor-alpha (TNF-α) is a cytokine that is significantly increased in Alzheimer’s disease (AD) and is closely associated with the development of neuropsychiatric symptoms." (PMID 36159454, 2022). "IL-1 beta, IL-6, IL-10, and TNF-alpha single nucleotide polymorphisms in human influence the susceptibility to Alzheimer’s disease pathology." (PMID 35966781, 2022).